RARA (retinoic acid receptor alpha)
Diseases named in the same sentence as RARA in open-access papers (continued):
Sharing a sentence is not in itself a finding about the gene and the disease.
breast adenocarcinoma (1 paper, 2016). "It is therefore tempting to speculate that E2-ERα, in addition to a direct effect on CXXC5 expression, also modulates the transcriptional output of CXXC5 by regulating gene expressions of and interactions with RARα and WT1 in breast tissue and breast adenocarcinomas." (PMID 27886276, 2016).
breast fibroepithelial tumors (1 paper, 2021). "The results showed that PAF did not carry the NAB2-STAT6 gene fusion in SFT or the genetic changes in breast fibroepithelial tumors, such as MED2, RARA, and FLNA." (PMID 34350112, 2021).
cataract (1 paper, 2024). Partial or complete opacity of the crystalline lens of one or both eyes that decreases visual acuity and eventually results in blindness. "Concerning eye development, transgenic mice expressing constitutively active RARA specifically in the lens exhibited microphthalmia, cataracts, and protrusion of aberrant lens tissue from the lens capsule, resembling the ocular defects observed with overexposure to retinoids in utero." (PMID 39450403, 2024).
cervical tumors (1 paper, 2025). "Additionally, RARA expression is reduced by 75% in cervical tumors compared to control tissues." (PMID 40168262, 2025).
cholesteatoma (1 paper, 2023). A pathologic process characterized by the proliferation of keratinizing squamous epithelium resulting in the accumulation of keratin and cells in the middle ear and/or mastoid.
coloboma (1 paper, 2019). An abnormality in which a part of a structure in one or both eyes is missing. "A recent report identified a de novo mutation in RARA in a coloboma patient which is hypothesized to impair the interaction between RA and RARA." (PMID 31796115, 2019).
craniosynostosis (1 paper, 2025). Craniosynostosis is defined as the premature fusion of one or more cranial sutures leading to secondary distortion of skull shape resulting in skull deformities with a variable presentation. "In addition to these disorders attributable to RA excess, a recurrent heterozygous nucleotide substitution of RARA, encoding p.(Gly289Arg) in RARα, was recently described in 2 individuals with craniosynostosis." (PMID 40519748, 2025).
cutaneous T-cell lymphoma (1 paper, 2017). "In addition, we evaluated the ability of the RXR ligand, bexarotene, to target RARA because of its clinical application in cutaneous T-cell lymphoma." (PMID 28412739, 2017). "While retinoids have been used to treat some cutaneous T-cell lymphomas (CTCLs), their mechanism of action and the role of RARA in CTCL and other mature T-cell lymphomas remain poorly understood." (PMID 28412739, 2017).
esophageal SCC (1 paper, 2005). "Since little is known about the abundance of RARs and RXRs protein in esophageal SCC in humans, the major focus of the present study was to determine protein levels of RARα, β, γ, and RXRβ in normal, macroscopically unaffected esophageal tissue and SCC of patients with untreated SCC and controls." (PMID 16277658, 2005). "Furthermore, in in situ studies a reduced mRNA expression of RARα was found in esophageal SCC compared with normal tissue." (PMID 16277658, 2005). "Therefore, the aim of the present study was to evaluate protein levels of retinoic acid receptors (i.e. RARα, β, γ, and RXRβ) in esophageal SCC and surrounding normal tissue of patients with untreated SCC and controls." (PMID 16277658, 2005). "Protein levels of RARα, β, γ, and RXRβ were determined by Western Blot in normal esophageal tissue and tissue obtained from SCC of 21 patients with newly diagnosed esophageal SCC and normal esophageal tissue of 10 controls." (PMID 16277658, 2005).
fertility disorders (1 paper, 2022). "Considering that the characteristic function of the RAR/RXR heterodimer is the regulation of downstream gene expression, we conjectured that RARα influenced the decidualization process in fertility disorders by acting as a transcription factor." (PMID 35663305, 2022).
food allergy (1 paper, 2021). Gastrointestinal disturbances, skin eruptions, or shock due to allergic reactions to allergens in food. "This study showed that RARα in DCs was involved in the microbiota dysbiosis-induced exacerbation of food allergy." (PMID 34721398, 2021).
glomerular diseases (1 paper, 2011). "Based on previous studies, we believe that RARα agonists would also protect against podocyte injury in other forms of glomerular diseases." (PMID 22125642, 2011).
glomerulosclerosis (1 paper, 2011). A hardening of the kidney glomerulus caused by scarring of the blood vessels. "Based on these findings, we conclude that BD4, a new RARα agonist, induces podocyte differentiation in vitro and improves proteinuria and glomerulosclerosis of HIV-1 transgenic mice in vivo." (PMID 22125642, 2011). "RARα agonists can reduce proteinuria and glomerulosclerosis and protect podocytes from injury." (PMID 22125642, 2011).
heart failure (1 paper, 2014). Inability of the heart to pump blood at an adequate rate to meet tissue metabolic requirements. "Understanding the mechanisms underlying the impaired cardiac expression/activation of RARα and RXRα will be important in determining the novel mechanisms leading to heart failure." (PMID 26237391, 2014). "Targeted disruption of RAR and RXR, mainly RARα and RXRα in the embryonic stage, resulted in early postnatal or embryonic lethality and heart failure, suggesting that RARα and RXRα are the two main receptor subtypes that are involved in the regulation of cardiomyocyte differentiation and function." (PMID 26237391, 2014).
Hepatitis (1 paper, 2021). Inflammation of the liver. "Treatment with retinoic acid (RA) attenuated Con A-induced hepatitis by directly altering retinoic acid receptor alpha (RAR-α) and mitogen-activated protein kinase- (MAPK-) related signaling molecules, which reduced IFN-γ and IL-4." (PMID 33506011, 2021).
HIV-1 infection (1 paper, 2011). The type species of lentivirus and the etiologic agent of acquired immunodeficiency syndrome (AIDS). "Next we tested the effect of the RARα antagonist on the HIV-1 infection in the DC-T cell cultures." (PMID 21738472, 2011).
HIV-associated nephropathy (1 paper, 2023). Renal disease in human immunodeficiency virus (HIV)-infected patients. "Therefore, BD4 appeared to be a new proof-of-concept RARα agonist, which could be used as a potential therapy for patients with kidney diseases, such as HIV-associated nephropathy (HIVAN)." (PMID 36770721, 2023).
Hydrocephalus (1 paper, 2023). Hydrocephalus is an active distension of the ventricular system of the brain resulting from inadequate passage of CSF from its point of production within the cerebral ventricles to its point of absorption into the systemic circulation. "Importantly, the mechanism of RARα on hydrocephalus was associated with MAFB, MSR1, and neuroinflammation." (PMID 36768908, 2023). "We identified RARα as a role in regulating macrophage/microglia infiltration in choroid plexus after hydrocephalus." (PMID 36768908, 2023). "In conclusion, activation of the RARα attenuated CSF hypersecretion to inhibit hydrocephalus development via regulating the MAFB/MSR1 pathway." (PMID 36768908, 2023). "Taken together, the current outcomes demonstrated that activation of the RARα attenuated CSF hypersecretion to inhibit hydrocephalus development, at least in part through the MAFB/MSR1 pathway." (PMID 36768908, 2023). "In this study, we confirmed that RARα might affect the occurrence and development of hydrocephalus through MSR1-mediated neuroinflammation." (PMID 36768908, 2023). "Inflammation is strongly associated with the development of hydrocephalus, suggesting that RARα-targeted therapy may be beneficial in hydrocephalus." (PMID 36768908, 2023). "Our investigation aims to determine the potential role and mechanism of RARα in hydrocephalus." (PMID 36768908, 2023). "RARα may act as a possible therapeutic target for hydrocephalus." (PMID 36768908, 2023). "Hence, RARα might be a possible therapeutic target to alleviate hydrocephalus." (PMID 36768908, 2023). "However, previous studies have not studied the therapeutic effect of Am80 in hydrocephalus, and the particular protective mechanism following RARα stimulation remains unknown." (PMID 36768908, 2023).
Hyperglycemia (1 paper, 2019). An increased concentration of glucose in the blood. "In conclusion, these data demonstrate that the selective RARα agonist AM80 exacerbates HFD-induced NAFLD and hyperglycemia." (PMID 30677086, 2019).
Hypoalbuminemia (1 paper, 2021). The concentration of albumin in the blood circulation is below the lower limit of normal. "Previous studies reported that these factors increased the risk of APL thrombosis, including male, high score performance status (PS), high white blood cell count and platelet count, low fibrinogen levels, hypoalbuminemia, PML/RARa fusion gene variant, CD2/CD15 and FLT3-ITD positive." (PMID 34130694, 2021).
idiopathic pulmonary arterial hypertension (1 paper, 2022). A sporadic form of pulmonary arterial hypertension (PAH) characterized by elevated pulmonary arterial resistance leading to right heart failure. "In plasma of idiopathic pulmonary arterial hypertension patients, the RARα gene is expressed in cultured human pulmonary artery smooth muscle cells." (PMID 36147486, 2022).
Insulin resistance (1 paper, 2014). Increased resistance towards insulin, that is, diminished effectiveness of insulin in reducing blood glucose levels. "Our group also reported that ATRA, Am580 (RARα selective ligand) and LGD1069 (RXR ligand) lowered the blood glucose level and improved insulin resistance in a Zucker diabetic fatty (ZDF) rat type 2 diabetic model." (PMID 26237391, 2014).
intestinal inflammation (1 paper, 2021). "To evaluate the RA signaling impact on allergic intestinal inflammation, we generated a cell-specific loss-of-function mouse model of RARα." (PMID 34721398, 2021).
ischemia (1 paper, 2014). A hypoperfusion of the BLOOD through an organ or tissue caused by a PATHOLOGIC CONSTRICTION or obstruction of its BLOOD VESSELS, or an absence of BLOOD CIRCULATION. "Inhibition of PI3K/Akt, AMPK, ERK1/2 and ROR-α (retinoic-acid receptor alpha) pathway led to significant decrease of FGF21 induced cardio-protection and restoration of cardiac function in response to global ischemia." (PMID 24498293, 2014).
laryngeal carcinoma (1 paper, 2017). Carcinoma that arises from the laryngeal epithelium. "ATRA enhances the suppressive role of RARα on miR-27a promoter and release the inhibition of miR-27a on GSK-3β leading to laryngeal cancer differentiation through GSK-3β-involved Wnt/β-catenin pathway." (PMID 28122350, 2017).
liver fibrosis (1 paper, 2025). "Hepatocyte NRP-1, whose expression is upregulated by HGF by binding the transcription factor RARA to its potential promoter regions, promotes liver fibrosis via the c-Met signaling pathway." (PMID 40419692, 2025). "Targeting the HGF/RARA/NRP-1 axis may offer a promising therapeutic strategy for managing liver fibrosis, potentially by developing drugs that modulate NRP-1 expression or function." (PMID 40419692, 2025). "HGF further upregulates NRP-1 through the transcription factor RARA, exacerbating liver fibrosis." (PMID 40419692, 2025).
metastasis (1 paper, 2017). The spread or migration of cancer cells from one part of the body (where they first appeared) to another. "Clinicopathological analysis revealed that overexpression of RARα was strongly correlated with tumor diameter, lymph node metastasis and clinical stages in GC patients." (PMID 28035062, 2017).
nephrotic syndrome (1 paper, 2026). A collection of symptoms that include severe edema, proteinuria, and hypoalbuminemia; it is indicative of renal dysfunction. "Differentially altered expression of transcripts of retinoic acid receptors α, β, γ (Rarα, β, γ), which mediate the actions of all-trans retinoic acid (RA), is observed in glomeruli of nephrotic syndrome (NS) patients vs normal individuals, with Rarβ reduced and both RARα and RARγ increased." (PMID 41364431, 2026).
nyctalopia (1 paper, 2024). "Unlike fenretinide, another RBP4 antagonist, A1120 is neither a retinoid nor an agonist to RARα, the property of which may avoid the retinoids‐associated side effects, such as nyctalopia and delayed dark adaptation." (PMID 39031684, 2024).
orofacial cleft (1 paper, 2018). A disorder of facial skeleton that is characterized by cleft lip and/or cleft palate that result in feeding, speech and hearing problems caused by failures during development. "There is some evidence in the literature linking vitamin A itself and genes related to vitamin A, e.g., retinoic acid receptor alpha, RARA, with the risk of orofacial clefts." (PMID 29535761, 2018).
pancreatic ductal adenocarcinoma (1 paper, 2023). An infiltrating adenocarcinoma that arises from the epithelial cells of the pancreas. "Intriguingly, downregulation of the expression of RARα and RARβ has been reported in pancreatic ductal adenocarcinoma and associated with better overall survival." (PMID 37569466, 2023). "Real-time RT-PCR examination of the expression of RARs revealed downregulation of RARα, RARβ, RXRα, and RXRβ in pancreatic ductal adenocarcinoma tissue." (PMID 37569466, 2023).
peanut allergies (1 paper, 2023). "Advances have been shown for recombinant allergens like rPru p 343,44 in peach allergies and rAra h 1, 2, 3 in peanut allergies." (PMID 37822702, 2023).
psoriasis plaques (1 paper, 2022). "In fact, we found that the retinoic acid receptor alpha (RARA) is the target of a plethora of chemical compounds already employed in the treatment of severe psoriasis plaques." (PMID 36437479, 2022).
refractive error (1 paper, 2009). A defect in the focusing of light on the retina as in astigmatism, myopia, or hyperopia. "Alternative mechanisms of action such as those mediated by epigenetic effects or those that affect gene expression may play a role and this needs to be further explored to fully understand what role, if any, RARA has in the development of refractive errors." (PMID 19626135, 2009). "Additional research exploring the possible role for RARA in the development of refractive errors via mechanisms that do not involve direct changes in the nucleotide sequence is also warranted." (PMID 19626135, 2009).
retinal diseases (1 paper, 2022). "Apoptosis is also a characteristic hallmark of retinal diseases, so BBC3 and BCL2L13, RARA were investigated, as well as genes (EFEMP1, CFH) involved in the regulation of methylation sites." (PMID 36078063, 2022).
rhabdomyosarcoma (1 paper, 2017). A rare aggressive malignant mesenchymal neoplasm arising from skeletal muscle. "MiR-27a contributes to rhabdomyosarcoma cell proliferation by suppressing RARα and RXRα." (PMID 29137318, 2017). "MicroRNA-27a contributes to rhabdomyosarcoma cell proliferation by suppressing RARA and RXRα." (PMID 29137318, 2017).
skin eruptions (1 paper, 2023). "Two genetic variants of the retinoic acid receptor alpha (RARA) gene have been significantly associated with critical skin toxicity (including patients with desquamation and acneiform skin eruptions)." (PMID 36990917, 2023).
T-cell lymphomas (1 paper, 2017). "After identifying a PTCL with a RARAR394Q mutation, we sought to characterize the role of RARA in T-cell lymphoma cells." (PMID 28412739, 2017). "Taken together with the relative specificity of AM80 for RARA, these findings strongly support and extend our in vitro functional observations that RARA drives cell cycle progression and, more specifically, G1-S transition, in T-cell lymphoma cells." (PMID 28412739, 2017). "Having identified a role for RARA in driving T-cell lymphoma cell growth, we next examined the effect of RARA on the cell cycle." (PMID 28412739, 2017). "Because we showed that RARA drove T-cell lymphoma cell growth and cell-cycle progression, we next examined the ability of retinoids to reverse these effects." (PMID 28412739, 2017). "In conclusion, RARA drives cyclin-dependent kinase expression, G1-S transition, and cell growth in T-cell lymphoma." (PMID 28412739, 2017). "To investigate the role of wild-type RARA (RARAwt) and RARAR394Q, we utilized three mature T-cell lymphoma cell lines with varied native RARA expression: one RARAhigh cell line (Mac-1) and two RARAlow cell lines (Karpas 299 and HuT78)." (PMID 28412739, 2017). "Since this mutation had not been previously reported and the role of RARA in PTCL had not been characterized, we investigated the role of RARA in the growth and chemosensitivity to retinoids in T-cell lymphoma cells." (PMID 28412739, 2017).
testicular embryonal carcinoma (1 paper, 2015). A malignant germ cell neoplasm arising from the testis. "Results from this present study demonstrate that PPARβ/δ attenuates tumor progression in testicular embryonal carcinoma, in part, through interfering with RARα signaling and suppressing MMP2-mediated cell invasion and migration." (PMID 26431381, 2015).
testicular germ cell tumor (1 paper, 2015). A germ cell tumor arising from the testis. "This study suggests that specific modulation of RARα signaling may be a viable approach for the treatment of testicular germ cell tumors." (PMID 26431381, 2015).
vitamin deficiency (1 paper, 2024). A disorder that is caused by the deficiency of a vitamin. "Considering that vitamin deficiency may therefore modulate furin expression, we sought to elucidate the interaction of RARα with the furin promoter in our chronic vitamin A deprivation (VAD) model." (PMID 38674868, 2024).